CD55 (CD55 molecule (Cromer blood group))
Diseases named in the same sentence as CD55 in open-access papers (continued):
Sharing a sentence is not in itself a finding about the gene and the disease.
colorectal cancer (18 papers, 1992 to 2026). A primary or metastatic malignant neoplasm that affects the colon or rectum. "CD55, a regulator of complement activation, is frequently overexpressed in colorectal cancers and linked to poor prognosis, with its inhibition showing promise as a treatment strategy." (PMID 41550766, 2026). "Compared with colorectal cancer alone, CD55 also has a certain diagnostic ability for detecting organ metastasis." (PMID 40596619, 2025). "Elevated CD55 concentrations in stool specimens have been proposed to have diagnostic value for patients with colorectal cancer." (PMID 31024572, 2019). "The cancer vaccine 105AD7 is an anti-idiotypic monoclonal antibody that mimics the tumour-associated antigen 791T/gp72 (CD55, Decay Accelerating Factor) on colorectal cancer cells." (PMID 11384090, 2001). "CD55 is a potential tumor promoter and diagnostic marker for colorectal cancer." (PMID 40596619, 2025). "Although we did not observe the efficacy of reducing CD55 expression in mouse tumors, our study found that CD55 can be a potential tumor marker for the diagnosis of colorectal cancer." (PMID 40596619, 2025). "Immunohistochemical images from the HPA database showed that the expression CD55 was higher in colorectal cancer than in adjacent normal tissue." (PMID 36741376, 2022). "Using the TIMER2.0 online program, we found that CD55 was highly expressed in a variety of solid cancers, including colorectal cancer." (PMID 36741376, 2022). "A recent study have demonstrated the anti-proliferative and anti-metastatic role of anti-CD55 monoclonal antibody in colorectal cancer cells." (PMID 33758996, 2022). "A similar expression of CD55 is reported in human colorectal cancer, which is likely to reflect variability in the o-glycosylation of the protein in tumor cells." (PMID 33808725, 2021). "CD97 and CD55 have been shown to be upregulated in a variety of solid tumors, including gastric and colorectal cancers." (PMID 25624904, 2015). "In line herewith, CD55 overexpression has been a target for intestinal tumor imaging, conferring with a poor prognosis in colorectal cancer patients." (PMID 25596646, 2015). "Subsequently, cell experiments proved that CD55 can promote the proliferation and migration of colorectal cancer cell lines, and by collecting clinical samples from colorectal cancer patients, it was proved that it can be used as a potential clinical diagnostic marker." (PMID 40596619, 2025). "This study proves that the complement system plays an important role in colorectal cancer and found that CD55 can promote colorectal proliferation and metastasis, which may also become a potential tumor marker for the diagnosis of colorectal cancer." (PMID 40596619, 2025). "Additionally, CD55 overexpression predicts poorer clinical outcomes in colorectal cancer, with stromal CD55 overexpression correlating with unfavorable prognostic markers." (PMID 40370471, 2025). "In 2019, a novel CD55 chimeric mAb displayed efficacy against colorectal cancer cells." (PMID 38612911, 2024). "Further longitudinal studies of the link between CD55 and progression of IM could demonstrate the potential of CD55 as a therapeutic target, as previously explored in colorectal cancer." (PMID 35851954, 2022). "IHC studies of tumour samples from various stages of colorectal cancer, however, showed that CD59 and CD55 expression is far less frequent than seen with our tumour cell lines." (PMID 15655555, 2005). "As long as colorectal cancer occurs, the content of CD55 increases significantly regardless of whether there is metastasis, and it has a very effective diagnostic efficacy." (PMID 40596619, 2025). "Interestingly, despite producing anti-CD55 immune responses as an adjuvant agent, 105AD7 did not prolong survival in a double-blind colorectal cancer phase II trial." (PMID 38612911, 2024).
colorectal cancer (continued). "In 5/88 colorectal carcinomas DAF(CD55) was localised on the apical cell surface of all tumour cells, 31/88 were completely negative, 52/88 expressed DAF(CD55) in parts of their neoplastic populations." (PMID 1384641, 1992).
gastric cancer (18 papers, 2009 to 2025). A primary or metastatic malignant neoplasm involving the stomach. "This is the first long-term follow-up of a clinical trial assessing an additive treatment for stomach cancer consisting of a fully human IgM antibody directed specifically against the tumour-specific CD55PAT-SC1 variant of CD55." (PMID 24452482, 2014). "The epitope identified by PAT-SC1 is a carbohydrate found on the decay acceleration factor-B (DAF/CD55), a protein overexpressed on the membrane of gastric cancer cells." (PMID 38629061, 2024). "High‐level expression of decay‐accelerating factor, CD55, has previously been found in human gastric cancer (GC) and intestinal metaplasia (IM) tissues." (PMID 35851954, 2022). "Antibodies against CD55 have been already used as additive therapeutic agents in the treatment of patients with breast and gastric cancer." (PMID 27043658, 2016). "Early-stage gastric carcinomas are easily exposed to the complement attack environment, and tumor cells expressing CD55 protein can escape complement lysis." (PMID 26233326, 2016). "Our previous studies revealed that strong co-expressions of CD97 and its ligand CD55 were exclusively localized at the tumor invasion front of gastric cancer, and additionaly correlated with its TNM status." (PMID 22768192, 2012). "IgM SC-1 recognizes a tumor-specific carbohydrate epitope on decay-accelerating factor B (DAF; also known as CD55), which is selectively expressed on the membrane of gastric carcinoma cells, and induces apoptosis through receptor crosslinking both in vitro and in experimental in vivo models." (PMID 41357197, 2025). "CD55 is a member of membrane-bound complement-regulatory proteins and could be useful as molecular markers for prognosis and therapy of gastric carcinoma patients." (PMID 29283424, 2017). "CD55 has been used previously as a prognostic biomarker in gastric cancer." (PMID 24073403, 2013). "In the 6 gene set, CD55 has been used previously as a prognostic biomarker in gastric cancer." (PMID 19208118, 2009). "In the human stomach cancer cell line, 70 kDa and 82 kDa variants of the CD55 protein have been reported, and we suspected that the band detected in both Mock and fDAF-expressing sEC cells may be the human DAF protein." (PMID 25671605, 2015). "For instance, negative regulators of complement (such as CD46, CD55, and CD59) have been found to be highly expressed in gastric cancers, which could potentially explain why T+P therapies failed to offer a significant clinical benefit in the JACOB Phase III trials of gastric HER2+ cancers." (PMID 35167491, 2022).
COVID-19 (16 papers, 2020 to 2025). A disease caused by infection with severe acute respiratory syndrome coronavirus 2. "A significantly higher CD55 expression in blood monocytes of COVID-19 patients was observed compared to healthy controls." (PMID 39337843, 2024). "The CD55 increase observed in these distinct cell populations of COVID-19 patients was reported as a characteristic feature of COVID-19." (PMID 38178176, 2024). "The previous study has found higher CD46, CD55, and CD59 levels in monocytes of COVID-19 patients than in healthy people, especially CD55 levels correlated with plasma inflammatory markers such as CRP and serum amyloid A during acute infection." (PMID 36820087, 2023). "In silico microarray data analysis from the ArrayExpress database revealed possible involvement of CD55 differential expression in COVID-19." (PMID 37795240, 2023). "Our findings provide insights into the role of the complement system in the pathogenesis of COVID-19 showing early activation on monocytes with a potentially compensatory upregulation of the complement inhibitor CD55." (PMID 35250994, 2022). "We demonstrate in a cohort of primarily hospitalized patients with acute COVID-19 that there is increased complement deposition on the cell surface of monocytes with a possibly compensatory upregulation of the CD55 complement inhibitor." (PMID 35250994, 2022). "There were similar expression levels of complement inhibitory receptors between COVID-19 recovered patients and HCs consistent with the initial increase in CD55 returning to normal levels post-recovery from COVID-19." (PMID 35250994, 2022). "Genetic variants of several complement regulatory proteins andfactors, including CD55(DAF), CFH, C3, C4BPA, and COLEC11, have been associated with adverse COVID-19 clinicaloutcomes." (PMID 34436508, 2021). "There could be a possible discrepancy in CD55 expression in hypoxic lung tissue in comparison to the peripheral blood cells in COVID-19 patients." (PMID 39337843, 2024). "However, CD55 was found to be upregulated on the surface of monocytes in COVID-19 patients when compared to healthy controls, especially in lung tissue." (PMID 37795240, 2023). "Interestingly, the cell surface-bound complement inhibitor CD55 was also upregulated in COVID-19 patient monocytes in comparison with HC cells." (PMID 35250994, 2022). "Greater cellular expression and/or deposition of complement markers on monocytes occurs in acute COVID-19 and is associated with a concomitant rise in CD55 but not CD59 expression." (PMID 35250994, 2022). "Furthermore, targeting CD55 upregulation as a potential therapy could be an option for post-infectious complications of COVID-19 and other inflammatory lung diseases in the future." (PMID 39337843, 2024). "However, upregulation of the CD55 inhibitory receptor may play a vital role in controlling complement activation and preventing the dramatic increases seen in those with severe COVID-19." (PMID 35250994, 2022). "Particularly, many inflammation genes, such as C5AR1, CD55, CSF3R, CXCL8, FPR1, KLF6, and NFKB1A, were significantly upregulated in Neu and Mono cells of the bone marrow of COVID-19 patients." (PMID 37087411, 2023). "None of these markers, however, was associated with disease severity, since similar surface expression of mC1q, mC3, CD55 and CD59 was observed when COVID-19 patients were grouped in mild-moderate versus severe disease." (PMID 35250994, 2022). "Genes involved in macrophage and neutrophils were over-expressed in patients infected with viruses (COVID-19 and INFL) compared to HLTY (“ascending” pattern, e.g. CLEC4D and CD55)." (PMID 34135895, 2021). "Thus, it is possible that preventing the formation of C3 via CD55 could be beneficial in COVID-19." (PMID 33318519, 2020). "Our study aims to highlight the histopathological features as well as CD55 protein expression in the COVID-19-related or COVID-19 non-related damaged lung tissue in comparison to non-damaged lung tissue." (PMID 39337843, 2024).
COVID-19 (continued). "Interestingly, expression of both CD55 and CD59 membrane-bound complement inhibitors was found specifically elevated in intermediate CD14highCD16+ monocytes from COVID-19 patients when compared to HCs (respectively)." (PMID 35250994, 2022). "Interestingly, we found elevated CD55 but not CD59 monocyte surface expression levels in COVID-19 patients when compared to the control group, consistent with a compensatory mechanism in the setting of persistent complement activation." (PMID 35250994, 2022). "CD55 and CD59, but not CD46, are involved in the hyperactivation and deposition of the complement factors C3, C3b/iC3b/C3d and C5b-9 in infected lung lesions of coronavirus disease 2019 (COVID-19)-affected people." (PMID 39599800, 2024).
Protein-losing enteropathy (15 papers, 2018 to 2025). Abnormal loss of protein from the digestive tract related to excessive leakage of plasma proteins into the lumen of the gastrointestinal tract. "CD55 deficiency with hyper-activation of complement, angiopathic thrombosis, and protein-losing enteropathy (CHAPLE) disease is a newly identified condition with an estimated worldwide prevalence of < 100 patients." (PMID 39934837, 2025). "The CD55 variant associated with protein-losing enteropathy and shown in cell studies to cause loss of CD55 on the cell surface also lacks a star rating, illustrating how the absence of this rating should not be used to exclude variants as disease-causing." (PMID 40554605, 2025). "A final example is CD55 deficiency with hyperactivation of complement, angiopathic thrombosis, and protein-losing enteropathy (CHAPLE) disease." (PMID 40519165, 2025). "CD55 deficiency with hyper-activation of complement, angiopathic thrombosis, and protein-losing enteropathy (CHAPLE) disease is ultra-rare (< 100 children or young adults worldwide) and potentially fatal." (PMID 39118150, 2024). "Pozelimab-bbfg has been approved for the treatment of another ultra-rare hereditary disease known as CD55-deficient protein-losing enteropathy also known as CHAPLE disease." (PMID 38530400, 2024). "CD55 deficiency with hyper-activation of complement, angiopathic thrombosis, and protein-losing enteropathy (CHAPLE) disease is an ultra-rare, potentially fatal condition caused by mutations in the CD55 gene." (PMID 39118150, 2024). "Loss of CD55 causes primary intestinal lymphangiectasia and protein-losing enteropathy, which can result in severe abdominal pain, chronic/recurrent diarrhea, vomiting, and edema that can require frequent hospitalizations and medical interventions." (PMID 39118150, 2024). "Isolated congenital CD55 deficiency is rare but has been observed in patients suffering from severe early-onset protein-losing enteropathy, whereas severe Guillain-Barré-like neurological symptoms with hemolysis are the hallmark of isolated CD59 deficiency." (PMID 32064578, 2020). "CHAPLE, which stands for CD55 deficiency with hyper-activation of complement, angiopathic thrombosis, and severe protein-losing enteropathy, results from CD55 deficiency leading to a hyperactivated complement system that mediates the formation of the membrane-attacking complex." (PMID 38530400, 2024). "More recently, a clinical link between CD55 and enteropathy has been described, reporting a life-threatening gastrointestinal disorder manifested in the eponymous CD55 deficiency with hyperactivation of complement, angiopathic thrombosis, and protein-losing enteropathy (CHAPLE) syndrome." (PMID 34698894, 2021). "CD55 is a known complement regulatory protein, and humans with defects in CD55 develop complement hyperactivation, angiopathic thrombosis, and protein-losing enteropathy (CHAPLE disease), a lethal illness that is due to overactivation of complement and innate immunity." (PMID 36036625, 2022). "Recently we have described patients who carry nonfunctional CD55, which led to protein-losing enteropathy." (PMID 37875972, 2023).
lung carcinoma (14 papers, 2017 to 2025). "We found that significantly higher lung cancer risk was linked with CD55 rs2564978 CC genotype (OR = 1.52, 95% CI = 1.11−2.07) or CT genotypes (OR = 1.34, 95% CI = 1.05−1.71), compared to the TT genotype." (PMID 28008159, 2017). "We then performed stratification analysis to evaluate the association of CD55 rs2564978 genotypes with lung cancer." (PMID 28008159, 2017). "We found that C allele of rs2564978 was associated with reduced expression of CD55 compared with the T allele in lung cancer cells." (PMID 28008159, 2017). "In the present study, we found that the CD55 rs2564978 T > C variant significantly decreased the transcriptional activity in lung cancer cells and contributed to an increased risk of NSCLC." (PMID 28008159, 2017). "Currently, it is unclear if the polymorphism located in the promoter CD55 is associated with the risk of developing lung cancer." (PMID 28008159, 2017). "However, we didn't find that CD55 rs2564978 T > C variant effected on the risk of lung cancer when stratified by the smoking intensity." (PMID 28008159, 2017). "As a key regulator of C3 and C5, the effect of CD55 genetic variant to the risk of lung cancer might be altered by tobacco smoke." (PMID 28008159, 2017). "Thus, we analyzed the role of CD55 polymorphism in the development of lung cancer stratified by smoking status." (PMID 28008159, 2017). "In human lung cancers, the levels of CD55 and CD59 were found to be adversely related to the infiltration of immune cells that combat tumors and indicated a worse prognosis." (PMID 40515636, 2025). "In this study, we also found that several genes related to the inflammatory response, lymphocyte activation and innate immune response in the mucosa (Hp/Reg3g/Nupr1/Adam8/Cd55/Cfh/Ednrb) were upregulated in mice with EGFRL858R*PTEN-/- induced lung cancer." (PMID 38499532, 2024). "CD55 expression in lung cancer cell lines was validated by immunoblotting with an anti-CD55 antibody (ab54595; Abcam)." (PMID 29895866, 2018). "Treatment of H460 cells with 177Lu-anti-CD55 resulted in a 66.23% reduction in lung cancer cell invasion and a 61.51% reduction in migration." (PMID 29895866, 2018). "CD44, CD166, and CD55 are known CSC cell surface markers in lung cancer and other cancer types." (PMID 36499099, 2022). "Given that cisplatin is an effective therapy for early- to advanced-staged lung cancer, combined cisplatin and 177Lu-anti-CD55 therapy could be effective for various types of lung cancer." (PMID 29895866, 2018). "CD55 was expressed in 68.89% (31/45) of lung cancer tissue specimens." (PMID 29895866, 2018). "We focused on whether 177Lu-anti-CD55 could improve quality of life in advanced lung cancer patients." (PMID 29895866, 2018). "However, studies also demonstrated a down-regulated expression of CD55 in ovarian cancer and lung cancer tissues." (PMID 28008159, 2017). "Our results suggested that CD55 rs2564978 variant was related to lung cancer among smokers, but not among non-smokers." (PMID 28008159, 2017). "Therefore, we examined whether 177Lu-anti-CD55 inhibited lung cancer cell invasion and migration in vitro." (PMID 29895866, 2018). "The expression levels of complement regulatory proteins CD46, CD55, and CD59 are notably elevated in various tumors, including head and neck squamous cell carcinoma (HNSCC), colon cancer, renal cancer, lung cancer, and breast cancer." (PMID 39958348, 2025). "Reducing the expression of CD55 and CD59, which EGFR heightens, can trigger the complement system and enhance lung cancer sensitivity to checkpoint inhibitors." (PMID 40515636, 2025). "Increased expression of CD55, CD46 and CD59 has been documented in lung cancer cells while another study showed increased factor H mRNA in lung cancer biopsies." (PMID 38178176, 2024).
lung carcinoma (continued). "A 16-week, 3 times a week, 60-minute low-intensity simplified 24-form Tai Chi training significantly attenuated CD55 expression but did not alter the CD4+ : CD8+ ratio in lung cancer survivors." (PMID 33777155, 2021). "We investigated whether CD55 was differentially expressed in lung cancer compared to normal tissue using immunohistochemistry." (PMID 29895866, 2018).